FAP (fibroblast activation protein alpha)
Diseases named in the same sentence as FAP in open-access papers (continued):
Sharing a sentence is not in itself a finding about the gene and the disease.
tumor (continued). "Firstly, FAP could act indirectly on tumor cells, as has been indicated by the finding that the depletion of FAP indirectly inhibits tumor cell proliferation via an enhancement of collagen accumulation and the impediment of myofibroblast content." (PMID 36263225, 2022). "Furthermore, FAP+ CAFs are considered the principal source of CXCL12 and IL-6, which have been implicated in the prevention of T cell accumulation/activity in the tumor." (PMID 36627901, 2022). "Currently, much research has been devoted to FAP as a protease in the tumor microenvironment." (PMID 35186170, 2022). "Hypomethylation in our study corresponds to abnormally high CAF marker expression in most tumors (except for FAP in THCA and TGCT), which indicates that CAF markers underlie a tumor-promoting behavior and may be potential new targets for epigenetic regulation." (PMID 36032075, 2022). "Our study showed that FAP expression levels in tumor tissues were elevated in GC patients." (PMID 36010886, 2022). "Univariate analysis revealed that sex, patient age, smoking, pathological stage, histological subtype, lymphocytic invasion, vascular invasion, pleural invasion, FAP expression in tumor cells, and FAP expression in CAFs were significant prognostic factors for recurrence." (PMID 35818720, 2022). "Furthermore, TNFα signaling and IL2/STAT5 signaling pathways were also enriched in FAP+ fibroblastsHighSPP1+ macrophagesHigh tumor samples." (PMID 35365629, 2022). "This binding of FAP also occurs in non-tumor tissue such as in hepatic fibrotic samples." (PMID 34988624, 2022). "Interestingly, the highest correlation (inverse) was noted for stromal FAP positivity and tumor PTEN status (corr = −0.31, P < 0.01) in MRI true-positive lesions." (PMID 36874403, 2022). "Furthermore, several tumor entities demonstrated strong expressions of FAP, such as 90% of all epithelial carcinomas, enabling precise and accurate diagnostic staging and, therefore the most suitable therapeutic approach for each individual patient." (PMID 34342669, 2022). "However, coculture with LSECs had negligible effects on the expression of FGFBP1 in tumor cells and the tumor cell–primed expression of FAPα in HSCs." (PMID 35951441, 2022). "However, in a subset of tumours, we also detected FAP expression in tumour cells, again demonstrating the existence of mesenchymal-like tumour cells in CMS4 CRC." (PMID 35296803, 2022). "Imaging of FAP-expression by [68Ga]Ga-FAPI PET/CT could provide insight in tumor characteristics because FAP-expression in adult normal tissue is low and generally undetectable." (PMID 36428657, 2022). "In this regard, our study design may provide a template to assess potential tumor–organ interactions for those FAP-directed molecular imaging or therapeutic probes." (PMID 35681588, 2022). "Tumor microenvironment fibroblasts overexpress the fibroblast activation protein (FAP)." (PMID 35631416, 2022). "Furthermore, PET imaging with a FAP-targeted antibody imaging probe, 89Zr-B12 IgG, was successfully evaluated in preclinical PC models, demonstrating high tumor uptake and long-term retention of the probe." (PMID 35052475, 2022). "Previous studies have shown that FAP plays an important role in predicting tumor aggressiveness." (PMID 35186170, 2022). "Next, we analyzed which cell populations within the tumor tissue express FAP." (PMID 36230765, 2022). "Fibroblast activation protein (FAP) could be a promising target for tumor imaging and therapy, as it is expressed in >90% of epithelial cancers." (PMID 36428657, 2022). "Moreover, FAP-specific CAR T transfer has been found to selectively recognizes and depletes the FAP+ subsets of cancer stem cells, which play a vital role in maintaining the tumor stroma and eliminating FAP+ CAFs." (PMID 36263225, 2022).
tumor (continued). "Furthermore, the expression comparison of FAPα versus Meflin or TIMP-1 in the same tumor of the 17 FFPE PDAC samples showed that higher-Meflin and/or higher-TIMP-1 than FAPα is involved in prolonged survival." (PMID 35773436, 2022). "High uptake and long retention in primary and metastatic tumor lesions and a reasonable toxicity profile warrant further investigation of 177Lu-FAP-2286 in prospective clinical studies to systematically evaluate its safety and efficacy and to define the patient population it would most benefit." (PMID 34168013, 2022). "In the present study, we could clearly confirm these results in NB, showing a strong FAP-IL-2-dependent increase in ADCC against tumor cells mediated by DB." (PMID 36230765, 2022). "The first of them, mAb F19, exhibited a tight selectivity for FAP+ fibroblasts in tumour tissues." (PMID 35158891, 2022). "Accordingly, anti-FAP vaccination has been reported in various tumor models." (PMID 35326670, 2022). "Interestingly, the vast majority of FAP-expressing tumour cells were derived from a tumour (SMC20) that was classified as CMS4." (PMID 35296803, 2022). "Thus, [68Ga]FAPI, a novel, recently developed tracer family targeting FAP shows a favorable tumor-to-background ratio and some important practical advantages regarding the scan preparations." (PMID 35349039, 2022). "Furthermore, the adoptive transfer of FAP-targeted CAT-T cells has been demonstrated to reduce tumor vascularity, ECM proteins, and glycosaminoglycans." (PMID 36263225, 2022). "Imaging techniques that target FAP are novel promising instruments for visualizing tumor stroma." (PMID 36566187, 2022). "Interestingly, we found that although tumor tissues with high infiltration of both FAP+ fibroblasts and SPP1+ macrophages showed high neoantigen features, they were characterized by non-silent richness and SNV neoantigens." (PMID 35365629, 2022). "Its use might enable a new kind of tumor development monitoring to predict if a tumor will spread and where potential metastases will appear due to a FAP positive environment." (PMID 34854061, 2022). "This suggests that the average FAP expression per individual stromal cell may be similar in CMS1 and CMS4 tumours but that the number of FAP-expressing cells is significantly higher in CMS4 CRC." (PMID 35296803, 2022). "FAP expression in tumor cells and stromal fibroblasts may involve tumor invasion since over-expression of FAP in epithelial cells or fibroblasts promoted cell invasion through extracellular matrix." (PMID 35252279, 2022). "FAP tracer uptake has been reported in various tumor entities." (PMID 34854061, 2022). "Therefore, imaging targeting FAP is considered a promising strategy for visualization of the tumor stroma, which is mainly composed of CAFs." (PMID 35785188, 2022). "TCGA database analysis shows that the FAP gene is highly expressed in most human tumor tissues." (PMID 35186170, 2022). "However, from a cancer biology perspective, this finding is very relevant because it demonstrates that mesenchymal-like tumour cells exist in cancer patients, and can be targeted through FAP." (PMID 35296803, 2022). "A monoclonal antibody conjugated with a tubulin binding drug maytrasinoid and a bispecific antibody simultaneously targeting FAP on CAFs and death receptor 5 on tumor cells has shown potent anti-tumor effects." (PMID 36010899, 2022). "FAP has also emerged as a potential candidate for directly targeting CAFs as it may be expressed by activated fibroblasts within tumor stroma and healing wound tissue." (PMID 35530322, 2022). "Indeed, we found that an epithelial differentiation signature was inversely correlated with FAP expression in individual tumour cells." (PMID 35296803, 2022). "However, the reports on PTRT are based mainly on peptides of the FAP inhibitors (FAPIs) 04 and 46, which showed a relatively short tumor-retention time in preclinical models and human subjects." (PMID 34556528, 2022).
tumor (continued). "However, there was significantly higher tumor-to-muscle ratio of [68Ga]Ga-DOTA-Siglec-9 in the FAP-IL2v-treated group than in the vehicle-treated group 7 days after baseline imaging (2.6 ± 0.091 vs. 2.1 ± 0.17, P = 0.026)." (PMID 35874707, 2022). "RT-PCR analysis revealed a clear FAP signal in all tumor tissue samples analyzed." (PMID 36230765, 2022). "Other applications include “cold” FAP-directed drugs, as relevant off-target effects may be reduced in individuals with high tumor load." (PMID 35681588, 2022). "Tumor cell–derived FGFBP1 induces FAPα expression in HSCs to promote vessel co-option." (PMID 35951441, 2022). "The PET imaging results of FAP-positive (HT-1080-FAP) and FAP-negative (HT-1080) tumor–bearing mice showed much higher uptake by FAP-positive tumors than by FAP-negative tumors, demonstrating that the higher tumor uptake was dependent on the FAP-targeting ability in vivo." (PMID 34593598, 2022). "Furthermore, the depleting of FAP-expressing cells (including all FAP+ CAFs), has been found to delay tumor growth in a subcutaneous model of PAAD." (PMID 36263225, 2022). "Moreover, the impact of soluble factors released from tumor cells on FAP expression by primary fibroblasts was assessed." (PMID 36230765, 2022). "Such evidence for the presence of CAF heterogeneity in PDAC has also been provided by immunostaining, in which CAF markers such as αSMA, podoplanin, PDGFRα/β, FSP1, and FAP have also been shown to differ in their staining intensity, distribution, and overlap across tumor tissue." (PMID 36010986, 2022). "At the same time, FAP-silenced SKOV3 cells can reduce tumor growth and inhibit CAF infiltration." (PMID 35681617, 2022). "In vivo studies verified that FAP-MB-5 could effectively reach the tumor sites to display selective activation for accurate tumor imaging and admirable PDT efficacy with minimal systemic side effects." (PMID 35664057, 2022). "Of note, ~3% of (epithelial) tumour cells showed atypical expression of FAP." (PMID 35296803, 2022). "The combinatorial treatment of resistant NB with DB and FAP-IL-2 in vivo effectively inhibited tumor growth, improved the survival of tumor-bearing mice and resulted in an increase in cytotoxic T and NK cells, as well as a reduction in Treg found in tumor tissue." (PMID 36230765, 2022). "FAP-2286 was developed with the hypothesis that an improved tumor retention time could be achieved using a cyclic peptide to target FAP compared to small molecule–based radiotracers." (PMID 35608703, 2022). "The SynCon FAP DNA vaccine reduces the number of FAP+ CAFs by targeting Fibroblast activation protein (FAP), a major marker of CAFs, thereby inducing T cell activation and suppressing tumor metastasis." (PMID 36532071, 2022). "Anti-CD8, identifies T cells, and anti-FAPα, identifies tumor stroma." (PMID 36278613, 2022). "Then, such modular designed BIVA probe highly enriched on tumor cell membrane through a dynamic ligand-receptor binding and sequently FAP-α triggered self-assembly process, resulting in a high contrast imaging with a signal-to-background ratio SBR over 9 folds." (PMID 35058435, 2022). "Thereby, FAP-MB-5 could serve as a promising FAPα- activatable theranostic photosensitizer owing to its accurate tumor imaging, remarkable tumor-specific PDT effect and favorable biosafety." (PMID 35664057, 2022). "The origin, number and distribution of FAP-expressing CAFs and the number of FAP molecules per cell may differ among tumours." (PMID 36698416, 2022). "Targeting FAP with antibodies, vaccines, or pharmacological agents could lessen tumor progression in several preclinical animal models." (PMID 36479116, 2022). "High FAP expression (H-score cut-off of ≥ 30) was observed in multiple tumor types." (PMID 35608703, 2022).
tumor (continued). "Therefore, we first evaluated the association of CXCL12, CXCR4, and FAPα mRNA expression with immune cell infiltration and procancer pathways in LARC using the Tumor IMmune Estimation Resource (TIMER) database and GSEA." (PMID 34976180, 2022). "QUESTION: How can tumor uptake and retention of the FAP-targeting molecular agents be optimized?" (PMID 34556528, 2022). "In addition, further research is warranted to tie the positive correlation of FAP intensity in the heart and tumor burden with a clinical meaning." (PMID 35681588, 2022). "Importantly, targeting FAP retains IL-2v within the tumor microenvironment, which selectively promotes an anti-tumor immune response." (PMID 35267548, 2022). "In addition, FAP levels in the tumor versus the stroma compartments were examined using automated imaging in a subset of cases with very high FAP staining across cancer types." (PMID 35608703, 2022). "Our work demonstrated that changes in tumor cell clustering may impact the efficacy of FAP-targeted RPTs, particularly with 225Ac due to the short radiation range." (PMID 36178531, 2022). "Reports suggest that ACTA2 and FAP may characterize somewhat overlapping but distinct CAF subpopulations in several tumor types." (PMID 35805064, 2022). "Here, single cell and spatial RNA sequencing of tumour and adjacent normal tissues reveals an interaction between FAP+ fibroblasts and SPP1+ macrophages that could be disrupted as an immunotherapy strategy." (PMID 35365629, 2022). "Tumor cells in the bordering areas adjacent to FAP-expressing CAFs are affected by radiobiological damage as a result of signals originating from irradiated cells, while the crossfire effect occurs within the range of the β-particles by traversing radiation penetrating several cell layers." (PMID 35608703, 2022). "As FAP is a marker observed in a subtype of AFs during inflammation, tissue injury and wound healing, as well as during tumor development, we can conclude that the mF lineage had different subpopulations of AFs while nF cells contained a small subpopulation of AFs." (PMID 36040985, 2022). "Targeting of FAP with therapeutic radionuclides is primarily intended to kill neighboring tumor cells, however destruction of CAFs may provide additional benefit." (PMID 36178531, 2022). "Immunohistochemical staining for FAP was performed on tumor specimens." (PMID 34870727, 2022). "A novel exosome-like nanoparticles was developed from fibroblast activation protein-α (FAP) engineered cancer cells as a tumor vaccine, which induced robust and specific cytotoxic T lymphocyte immunity against tumor cells and reprogrammed the immunosuppressive microenvironment." (PMID 36430471, 2022). "Due to abolished Fcγ receptor binding (P329G LALA mutations), FAP-IL-2v does not induce ADCC against FAP-positive cells and serves as a vehicle for IL-2v, transporting it into the tumor microenvironment." (PMID 36230765, 2022). "At 1 h p.i. of 111In-FAP-2286, tumor uptake was 11.1 percent injected dose per gram (%ID/g)." (PMID 35608703, 2022). "Finally, near-infrared photoimmunotherapy (NIR-PIT) is an innovative approach to CAF depletion that has been used to directly and specifically deplete FAP-expressing cells in the tumor microenvironment." (PMID 36010899, 2022). "Furthermore, depletion of FAP+ stromal cells in mouse tumor models disrupts the desmoplastic structure and promotes tumor growth." (PMID 35365629, 2022). "We detected FAP in tumor tissue, with major expression by tumor-infiltrating MDSC." (PMID 36230765, 2022). "Moreover, synchronously targeting both malignant cells and FAP+ stroma has been established to produce a robust anti-tumor effect." (PMID 36263225, 2022). "In most tumor types, FAP expression is associated with increased lymph node metastasis and decreased overall survival in various tumors." (PMID 34854061, 2022).
tumor (continued). "In addition to upregulating IFN-γ expression and attenuating the tumor immunosuppressive microenvironment, the eNVs-FAP vaccine also depletes FAP+ CAFs and simultaneously induces ferroptosis in tumor cells via two different pathways." (PMID 36422541, 2022). "Furthermore, the agent successfully delineated FAP-expressing tumors with high contrast images due to its increased tumor accumulation and favorable pharmacokinetics." (PMID 35163938, 2022). "Indeed, co-treatment of a CXCR4 inhibitor (AMD3100) with ICB in PDAC mice with an intact FAP+ CAFs population induced rapid T cell accumulation and significant tumor regression." (PMID 36671452, 2022). "In another way, changes in the stroma during tumor development may lead to changes in the expression of FAP, so whether different aspects of tumor variability may have an impact on FAPI imaging results needs to be further explored." (PMID 35692767, 2022). "The contribution of FAP + tumour cells to tracer retention is likely to be small." (PMID 35296803, 2022). "In multivariate analyses, high FAP expression in tumor cells was an independent predictive factor of both overall survival (OS; hazard ratio [HR] = 2.57, 95% confidence interval [CI]: 1.49–4.42, p < 0.001) and recurrence‐free survival (RFS; HR = 2.13, 95% CI: 1.38–3.29, p < 0.001)." (PMID 35818720, 2022). "It is believed that gaining a better understanding of the role of this protein in the FAP-mediated interaction between stroma and tumor cells could contribute to optimizing the FAP-inhibition strategy." (PMID 36263225, 2022). "In another strategy, nanoparticles such as FAP-targeted liposomes have been explored as carriers to specifically deliver therapeutic drugs (e.g., doxorubicin, anti-Tenascin C) to CAFs or to remodel the tumor microenvironment." (PMID 36010899, 2022). "Furthermore, several radiolabeled FAP inhibitors (FAPI) targeting FAP expression in CAFs and characterized by the rapid renal clearance and high tumor-to-background ratio (TBR) have been developed for PET imaging." (PMID 36428657, 2022). "Furthermore, FAP expression as analyzed by immunohistochemistry directly correlated with data obtained by autoradiography of matched tumor specimens using 111In-FAP-2286 as the detection reagent, suggesting that FAP-2286 binds specifically to FAP." (PMID 35608703, 2022). "In addition, if FAP is to be used as a tumour-specific target for molecular imaging, its expression in healthy normal tissue should be very low." (PMID 35296803, 2022). "Moreover, in an autochthonous model of pancreatic ductal adenocarcinoma, depleting FAP-positive CAFs induced T-cell accumulation in cancer cells and synergistically enhanced anti-tumor effects within PD-L1 immunotherapy." (PMID 35198057, 2022). "Moreover, stromal fibroblasts of tumors coinjected with exosomes exhibited elevated levels of active YAP1 and FAPα, concomitant with an enhanced fibrotic response within tumor tissues." (PMID 35986369, 2022). "Consequently, the adoptive transfer of FAP-CAR T has provided insights that will contribute to the further development of FAP+-specific stromal cell-targeted therapies for treating PAAD by targeting FAP+ cells in the tumor microenvironment." (PMID 36263225, 2022). "Another study found that CXCL12, which FAP+ CAFs secrete, inhibits the accumulation of cytotoxic T cells in the vicinity of the tumour and may direct tumour immune evasion in a human PDAC model." (PMID 36284087, 2022). "In addition, we found that FAP expression was significantly higher in tumor CAFs than those fibroblasts in normal tissue." (PMID 36401232, 2022). "The elevated level of FAP expression was related to a more advanced tumor stage in STAD." (PMID 35359436, 2022). "Moreover, several CARs have been developed that exert their anti-tumour effects by directly depleting CAF by targeting fibroblast activation protein α (FAP-α)." (PMID 35205725, 2022).